RN7SL791P (RNA, 7SL, cytoplasmic 791, pseudogene)
Gene: Miscellaneous RNA gene on chromosome 5 (146,656,401 to 146,656,695, reverse strand). Ensembl gene ENSG00000241291.
Homologues: Orthologues: chimpanzee Metazoa_SRP (99% identical), macaque Metazoa_SRP (94% identical). Paralogues in human: RN7SL1 (85% identical), RN7SL2 (85% identical), RN7SL45P (84% identical), RN7SL3 (83% identical), RN7SL126P (82% identical), RN7SL230P (82% identical), RN7SL665P (81% identical), RN7SL242P (81% identical), RN7SL7P (81% identical), RN7SL147P (80% identical), RN7SL218P (80% identical), RN7SL543P (80% identical), and 704 more.